CXCR4 (C-X-C motif chemokine receptor 4)
Diseases named in the same sentence as CXCR4 in open-access papers (continued):
Sharing a sentence is not in itself a finding about the gene and the disease.
progressive supranuclear palsy (2 papers, 2022 to 2025). A rare late-onset neurodegenerative disease characterized by supranuclear gaze palsy, postural instability, progressive rigidity, and mild dementia. "Emerging evidence indicates that CXCR4 is associated with neurodegenerative diseases, such as PD and progressive supranuclear palsy." (PMID 35938039, 2022).
proliferative diabetic retinopathy (2 papers, 2010 to 2023). Advanced retinopathy due to diabetes mellitus characterized by the formation of new vessels in the retina. "Odds ratios (ORs) and 95% confidence intervals (CIs) of proliferative diabetic retinopathy associated with SDF-1α/CXCR4 axis genotypic frequencies." (PMID 38075689, 2023). "Odds ratios (ORs) and 95% confidence intervals (CIs) of non-proliferative diabetic retinopathy associated with SDF-1α/CXCR4 axis genotypic frequencies." (PMID 38075689, 2023). "We investigated the expression of the components of this pathway, including c-kit, SCF, granulocyte colony-stimulating factor (G-CSF), endothelial nitric oxide synthase (eNOS), and the chemokine receptor CXCR4, in proliferative diabetic retinopathy (PDR) epiretinal membranes." (PMID 20596251, 2010).
rosacea (2 papers, 2022 to 2024). A chronic erythematous skin disorder that affects the face. "In rosacea lesions, the results showed that all hub genes were negatively correlated with resting mast cells, and 9 (except CXCR4) were negatively correlated with resting dendritic cells." (PMID 38321132, 2024). "It requires further study to determine whether the CXCL12/CXCR4 signaling pathway has a role in some rosacea and acne patients with itching and pain." (PMID 38321132, 2024). "The expression of CXCL10, MMP9, IL1B, CXCL8, and CXCR4 were co-regulated by IRF1, STAT1, STAT3, IKBKB, HDAC1, ETS1, and CEBPB, which were highly expressed in rosacea and acne lesions." (PMID 38321132, 2024). "In addition, CXCR4 is involved in the migration of mast cells and in this study, the expression of CXCR4 was significantly increased in FFA and rosacea." (PMID 36091020, 2022). "Therefore, there might be a complicated interplay between CXCR4, mast cells, and neuropeptides in the neurogenic inflammation of FFA and rosacea." (PMID 36091020, 2022).
schwannoma (2 papers, 2019 to 2020). A benign, usually encapsulated slow growing tumor composed of Schwann cells. "In this pilot cohort, [68Ga]Pentixafor PET/CT was able to detect all schwannomas with sufficient tumor-to-background and tumor-to-blood pool ratios and matched with membranous CXCR4 expression as assessed by immunohistochemistry." (PMID 31245296, 2019). "Patient #2 (maximum tumor extension: 30 × 35 mm) showed areas with mild CXCR4 expression in 37.5% of schwannoma cells and areas with moderate CXCR4 expression in 55.5% of tumor cells." (PMID 31245296, 2019). "We have found that treatment with CXCR4 antagonists reduces schwannoma growth in cell culture experiments (unpublished data)." (PMID 31245296, 2019). "On the other hand, 10 nM and 100 nM fMLF stimulation upregulated Fpr2 in RT4 schwannoma cells, and also increased levels of chemokine receptor CCR2 and CXCR4 as well as PKCβ." (PMID 33322305, 2020). "From these results using an in vitro RT4 schwannoma model, we can assume that chemokine receptors CCR2 and CXCR4 may serve as co-receptors of Fpr2 when Schwann cells of the distal nerve stump are stimulated with formylated peptides released from injured axons." (PMID 33322305, 2020).
serous ovarian cancer (2 papers, 2021 to 2022). "On the other hand, we explored for the first time the predictive and prognostic role of pCXCR4 in relation to CXCR4 in high grade serous ovarian cancer." (PMID 35397601, 2022). "• We explored for the first time the predictive and prognostic role of pCXCR4/CXCR4 TIC ratio in high-grade serous ovarian cancer." (PMID 35397601, 2022).
silicosis (2 papers, 2021 to 2026). Silicosis is a respiratory disease caused by breathing in (inhaling) silica dust. "Combined with our findings that CXCR4 was increased in silicosis lungs and the CXCR4/CXCL12 axis may contribute to the enhancement of cytokines with profibrotic effects." (PMID 34149803, 2021). "Consistently, the transcriptomic analysis of patients with advanced silicosis revealed up-regulated expression of IFN-γ, IL-10 and CXCR4, and the OX40L/OX40 signaling pathway." (PMID 34149803, 2021).
tongue squamous cell carcinoma (2 papers, 2015 to 2020). A squamous cell carcinoma that arises from the tongue. "We measured the effect of IL-1β on CXCR4 expression in human tongue squamous cell carcinoma Tca8113 cells." (PMID 26176534, 2015).
ulcer (2 papers, 2023 to 2025). "The elevated levels of SDF‐1α subsequently bind to CXCR4 on EPCs, thereby attracting these cells and promoting ulcer healing." (PMID 40948240, 2025).
Ureteral obstruction (2 papers, 2019 to 2022). Obstruction of the flow of urine through the ureter. "Although some genes, such as Ccl3 and Cxcr4, changed persistently, the changes of many genes were temporarily observed after unilateral ureteral obstruction." (PMID 30949209, 2019). "CXCR4 is markedly upregulated in kidneys that have undergone ureteric obstruction." (PMID 35015734, 2022). "Otherwise, many of these genes, such as Agt, Ccl12, Col3a1, Dcn, Itgb6, and Thbs2, were temporarily changed in these MSLCs expanded from the left kidney at only 7 days after ureteral obstruction, but the changes of Ccl3 and Cxcr4 were constantly observed during the 14 days of follow-up." (PMID 30949209, 2019).
ventricular septal defect (2 papers, 2015 to 2022). The presence of a defect (opening) in the septum that separates the two ventricles of the heart. "Knockouts involving the CXCL12/CXCR4 axis are known to cause ventricular septal defects (VSDs), and developmental disruption of aortic arch, pulmonary artery, and coronary artery in animal models." (PMID 36148060, 2022).
ZIKV infection (2 papers, 2022 to 2024). "Additionally, genes encoding cytokines and chemokines, including IL-1α, Il-1β, Cxcr4, and Cxcl10, were significantly upregulated in response to ZIKV infection, suggesting the presence of neuroinflammation." (PMID 39273400, 2024). "The process is mediated by the upregulation of C-X-C motif chemokine 12 (CXCL12) in monocyte during ZIKV infection, a key regulator of lymphocytes shifts across BBB into CNS parenchyma as it interacts with C-X-C chemokine receptor type 4 (CXCR4)." (PMID 35308394, 2022).
abscesses (1 paper, 2022). "Increased expression of CXCR4 on PMN localized within the lamina propria and in crypt abscesses is observed in colonic mucosa from individuals with active UC compared to quiescent disease." (PMID 36712325, 2022).
Adamantinomatous Craniopharyngioma (1 paper, 2020). A craniopharyngioma consisting of broad strands, cords and bridges of a multistratified squamous epithelium with peripheral palisading of nuclei. "For example, CXCL12 is generally overexpressed in adamantinomatous craniopharyngiomas, and the CXCL12/CXCR4 axis promotes tumor proliferation, migration, and invasion through PI3K/AKT signal pathway." (PMID 32381016, 2020).
adrenal tumor (1 paper, 2025). "Given that CT and CXCR4 imaging revealed no abnormal changes beyond the tumors, we opted to remove the left adrenal tumor while preserving the remaining adrenal tissue." (PMID 39375255, 2025).
adult T-cell leukemia (1 paper, 2019). "Notably, inhibition of the stromal cell-derived factor-1 alpha-CXCR4 axis by CXCR4 antagonists was effective for patients with adult T-cell leukemia." (PMID 30897788, 2019).
airway hyperresponsiveness (1 paper, 2014). "Given intranasally, AMD3100, a CXCR4 antagonist that inhibits SDF-1 mediated effects, attenuated allergen-induced lung-homing of EPC, vascularization of pulmonary tissue, airway eosinophilia and development of airway hyperresponsiveness." (PMID 25279605, 2014).
alcoholic liver diseases (1 paper, 2015). A disorder caused by damage to the liver parenchyma due to alcohol consumption. "Given that GB is a cytotoxic molecule, the increase in this phenotype (T-CD8+GB+CXCR4-) could be involved in contributing to alcoholic liver disease." (PMID 26151816, 2015).
allergic conjunctivitis (1 paper, 2013). "Because CXCL12 is a potent chemotactic factor for T and pre-B lymphocytes, plasma cells, and dendritic cells (DCs) and expression of SDF-1 (CXCL12) receptor (CXCR4) is also documented on eosinophils and mast cells - the two critical components in allergic conjunctivitis." (PMID 24024210, 2013).
aortic stenosis (1 paper, 2025). Aortic valve stenosis is a aortic valve disease caused by the incomplete opening of the aortic valve. "In summary, our study demonstrates that NAMPT-enriched MSC-derived exosomes effectively slow aortic stenosis progression in EC CXCR4 KO mice, improving valvular hemodynamics and cardiac function." (PMID 41516133, 2025). "Next, to explore the role of NAMPT-Exo in aortic stenosis, we administered three doses of NAMPT-Exo to 6-week-old EC CXCR4 KO AS mice, along with PBS control and MSC-Exo, in different groups once a week." (PMID 41516133, 2025).
aortic valve stenosis (1 paper, 2022). Aortic valve stenosis (AVS) is a condition characterized by narrowing of the heart's aortic valve opening. "CXCL12/CXCR4 signaling is essential in cardiac development and repair, however, its contribution to aortic valve stenosis (AVS) remains unclear." (PMID 36148060, 2022).
arterial disease (1 paper, 2025). "Given the critical role of CXCR4 in the signalling network associated with arterial disease, we are keenly interested in developing therapeutic strategies for this target." (PMID 39779470, 2025).
Ascites (1 paper, 2015). Accumulation of fluid in the peritoneal cavity (between the layers of the peritoneum that lines the abdomen). "Therefore, we next investigated the presence of CXCR4+ GC cells in peritoneal washings from the patients without clinically apparent ascites." (PMID 26110809, 2015).
autism spectrum disorder (1 paper, 2025). A spectrum of developmental disorders that includes autism, and Asperger syndrome. "In this study, through the analysis of CHD8A and CHD8B allelic deletion samples, we identified seven hub genes associated with Autism Spectrum Disorder (ASD): IGF2, FN1, CXCR4, COL11A1, ITGA6, LOX, and FBN2." (PMID 40526590, 2025). "CXCR4 and IGF2 play critical roles in neuronal migration and differentiation, and their dysregulation has been linked to abnormal neurodevelopment associated with Autism Spectrum Disorder (ASD)." (PMID 40526590, 2025).
autoimmune pancreatitis (1 paper, 2021). "The pancreatic expression of SDF-1/CXCL12 and its receptor CXCR4 was also studied in a subset of IgG4-RD patients with autoimmune pancreatitis (IgG4-RD AIP) and compared to what was observed in the pancreatic ductal adenocarcinoma (PDAC)." (PMID 34764871, 2021).
benign breast disease (1 paper, 2013). "Although based on few studies, CAIX, GLUT1, and CXCR4 showed profound lower expression rates in normal breast tissue and benign breast disease (p < 0.001), and high rates in carcinoma in situ." (PMID 24206539, 2013). "The marked lower expression prevalence of CAIX, GLUT1 and CXCR4 in benign breast disease and normal breast tissue is thus highly promising." (PMID 24206539, 2013).
benign ovarian tumor (1 paper, 2022). "Specifically, the CXCR4 protein was expressed in 7/40 (17.50%) of paired benign ovarian tumor tissues but in 37/61 (60.66%) of tumor tissues, notably in the cytoplasm of tumor cells." (PMID 35681259, 2022). "Interestingly, not all benign ovarian tumor tissues were negative for CXCR4, with some weak expression observed." (PMID 35681259, 2022).
benign renal tumors (1 paper, 2023). "Within benign renal tumors, high cytoplasmic and nuclear CXCR4 expression scores were seen for oncocytomas (cytoplasmic: 100.00, nuclear: 31.00)." (PMID 36982302, 2023).
bone osteosarcoma (1 paper, 2019). A usually aggressive malignant bone-forming mesenchymal neoplasm arising from the bone. "However, our preliminary studies indicated that expression of GILT did not inhibit the infection of GHOST cells, a cell line derived from human bone osteosarcoma, by HIV-1 strains utilizing either CCR5 or CXCR4 co-receptor (data not shown)." (PMID 31631785, 2019).
brain glioma (1 paper, 2017). A malignant glioma that involves the brain. "Chemokine receptor type 4 (CXCR4) has also been identified as a marker (Fig. 2C1,2) because it is highly expressed in the CD133+ brain glioma side population cells." (PMID 28615716, 2017).
breast disease (1 paper, 2013). "We extracted expression rates of carbonic anhydrase-IX (CAIX), glucose transporter-1 (GLUT1), C-X-C chemokine receptor type-4 (CXCR4), or insulin-like growth factor-1 receptor (IGF1R) in human breast disease, evaluated by immunohistochemistry." (PMID 24206539, 2013).
bronchiectasis (1 paper, 2022). Segmental, irreversible dilation of the bronchial tree resulting in the accumulation of secretions which leads to obstruction. "We detected reduced levels of the chemokine receptors CXCR1 and CXCR2 and an increased expression of the chemokine receptor CXCR4 on sputum neutrophils as compared to peripheral blood neutrophils, both in PCD and in bronchiectasis." (PMID 36528664, 2022).
bullous pemphigoid (1 paper, 2024). Bullous pemphigoid (BP) is the most common form of autoimmune bullous dermatosis. "The CXCR4/CXCL12 axis seems particularly associated with B-cells infiltration in single-cell analysis of SSc skin biopsies and is also involved in cutaneous B-cell infiltration in bullous pemphigoid." (PMID 39185406, 2024).
cavernous hemangioma (1 paper, 2022). A hemangioma characterized by the presence of cavernous vascular spaces. "The results suggested that: 1) the ligand-receptor interactions between CXCL12 and CXCR4 play a significant role in the immune responses in cavernous hemangiomas; and 2) the high expression of BTNL9 may cause checkpoint blockade in BTNL9+EC through the binding of BTNL9 to T-cells." (PMID 35865633, 2022). "The high co-expression of CXCR4 and GZMB suggested that pDCs function for anti-tumour as CD8+T cells in cavernous hemangiomas." (PMID 35865633, 2022).
cerebellar malformation (1 paper, 2019). Cerebellar malformations are diverse congenital anomalies frequently associated with developmental disability. "Taken together, these observations suggest CXCR4 gain of function mutations can be associated with cerebellar malformation, mild neuromotor and psychopathological dysfunction in WHIM patients." (PMID 30819232, 2019).
cerebral toxoplasmosis (1 paper, 2017). Infections of the brain caused by the protozoan toxoplasma gondii that primarily arise in individuals with immunologic deficiency syndromes (see also aids-related opportunistic infections). "We showed that cerebral toxoplasmosis leads to increased expression of CXCR4 on neutrophil granulocytes." (PMID 28680853, 2017). "Collectively, our findings revealed that the recruited Ly6G+CXCR4+ neutrophil granulocytes display a heterogeneity in the CNS with a repertoire of effector functions crucial in parasite control and immune regulation upon experimental cerebral toxoplasmosis." (PMID 28680853, 2017).
cervical (1 paper, 2014). "Our results provide novel insight of SDF-1α/CXCR4 signaling in tumor microenvironment which may be promising to further delineate molecular mechanism of cervical carcinogenesis." (PMID 25114911, 2014).
cervical disc degeneration (1 paper, 2024). "The data demonstrated that Ns therapy inhibited NPC apoptosis and relieved cervical disc degeneration, likely via the SDF-1/CXCR4 axis." (PMID 38949514, 2024). "In summary, Ns therapy mitigated cervical disc degeneration by decreasing NPC apoptosis in CS rats; this inhibition might be mediated by SDF-1/CXCR4 signaling." (PMID 38949514, 2024).
cervical squamous cell carcinoma (1 paper, 2015). A squamous cell carcinoma arising from the cervical epithelium. "We have furthermore shown that CXC chemokine receptor 4 (CXCR4), CXCR7 and epidermal growth factor receptor (EGFR) were more frequently expressed in cervical squamous cell carcinoma than adenocarcinoma." (PMID 25795131, 2015).
choroidal neovascularization (1 paper, 2015). An eye disorder described by the growth of new blood vessels that originate from the choroid through a break in the Bruch membrane into the sub–retinal pigment epithelium (sub-RPE) or subretinal space. "Stromal cell-derived factor-1 (SDF-1) has been confirmed to participate in the formation of choroidal neovascularization (CNV) via its two receptors: CXC chemokine receptors 4 (CXCR4) and CXCR7." (PMID 26288180, 2015).
chronic hepatitis (1 paper, 2016). An active inflammatory process affecting the liver for more than six months. "In contrast, constitutive FGFR1 signaling in LSEC under chronic hepatitis induces the predominance of CXCR4 over CXCR7 by augmenting CXCR4 expression, leading to a shift from pro-regenerative vascular niche to pro-fibrotic phenotype accompanied by the proliferation of activated HSCs." (PMID 29259692, 2016).
chronic hepatitis C (1 paper, 2021). "In patients with chronic hepatitis C, CXCR4 was increased in cirrhotic livers." (PMID 33635004, 2021).
chronic lymphocytic thyroiditis (1 paper, 2022). "Myeloid cells express chemokines (CXCL12 and CXCL10) as chemoattractants to recruit T cells expressing their receptors (CXCR4 and CXCR3), which is consistent with the pathological findings indicating chronic lymphocytic thyroiditis in P1 and P2 patients." (PMID 35515000, 2022). "Myeloid cells expressed genes (CXCL10 and CXCL12) for chemokines as chemoattractants to recruit T cells expressing CXCR4 and/or CXCR3 in T1 and T2 samples, but not in T3, which was in accordance with the histological assessment that indicated chronic lymphocytic thyroiditis in T1 and T2 samples." (PMID 35515000, 2022).
Chronic Obstructive Asthma (1 paper, 2022). Chronic airway obstruction caused by asthma. "Up-regulation of CXCR4 in fibrocytes of patients with chronic obstructive asthma is essential for mobilization of bone marrow-derived fibrocytes into the circulation." (PMID 35634326, 2022).